KIR3DL1 (killer cell immunoglobulin like receptor, three Ig domains and long cytoplasmic tail 1)
Diseases named in the same sentence as KIR3DL1 in open-access papers (continued):
Sharing a sentence is not in itself a finding about the gene and the disease.
Ascites (1 paper, 2023). Accumulation of fluid in the peritoneal cavity (between the layers of the peritoneum that lines the abdomen). "A decrease in the KIR2DL2 and KIR3DL1 genes may be a predisposing factor for the development of ascites." (PMID 37760846, 2023). "KIR2DL2 and KIR3DL1 suggest a predisposition to the development of ascites." (PMID 37760846, 2023). "A significantly increased frequency of KIR3DL1+ was observed among AC patients with grade II ascites relative to grade I patients (95.5% compared to 87.5% respectively; p = 0.211)." (PMID 37760846, 2023). "In conclusion, the absence of KIR2DL2 and KIR3DL1 genes may be a predisposing factor for the development of ascites in AC patients." (PMID 37760846, 2023). "However, the KIR3DL1 gene slightly decreased in AC patients without ascites compared with those with ascites (93.2% vs. 98.3%, respectively; OR = 4.262; 95% CI: 0.927–19.599, p = 0.048)." (PMID 37760846, 2023).
atherosclerosis (1 paper, 2022). A disease characterized by the build-up of fatty material and calcium deposition in the arterial wall resulting in partial or complete occlusion of the arterial lumen. "Several risk markers related to the immune response that have key roles in atherosclerosis were identified, including the top aging marker MMP8, disease markers KIR3DL1 and MAGEA6, network markers based on degree (RBM10, PJA2, and CMTM6), and network markers based on betweenness (IRAK1 and VAMP8)." (PMID 35706446, 2022).
cervical intraepithelial neoplasia (1 paper, 2025). "A study conducted on a population of Chinese women with cervical intraepithelial neoplasia revealed that, among various inhibitory KIR genes, the frequency of KIR3DL1 was higher in healthy controls compared to CN, suggesting its protective role." (PMID 40244151, 2025).
co-infection (1 paper, 2013). "Consequently, if this effect is independent of HIV co-infection, the absence of KIR3DL1 alleles may release inhibition, resulting in more efficient lysis of infected hepatocytes in a KIR3DS1-independent manner." (PMID 23613999, 2013).
cryoglobulinemia (1 paper, 2015). Cryoglobulinemia is a type of vasculitis that is caused by abnormal proteins (antibodies) in the blood called 'cryoglobulins.' At cold temperatures, these proteins become solid or gel-like, which can block blood vessels and cause a variety of health problems. "Furthermore, individuals with a HLA-Bw6 KIR3DL1+ combination of genes showed higher risk of developing lymphoma than cryoglobulinemia." (PMID 25700262, 2015).
dengue disease (1 paper, 2016). Dengue fever (DF), caused by dengue virus, is an arboviral disease characterized by an initial non-specific febrile illness that can sometimes progress to more severe forms manifesting capillary leakage and hemorrhage (dengue hemorrhagic fever, or DHF) and shock (dengue shock syndrome, or DSS). "However, the sample size was too small to draw any conclusions regarding associations between KIR3DL1 expression, KIR3DL1 subtyping and dengue disease severity." (PMID 26439909, 2016). "Our results define a specific interaction between the inhibitory receptor KIR3DL1 and a DENV‐derived CD8+ T cell epitope with potential relevance to the immunopathogenesis of dengue disease." (PMID 26439909, 2016).
Encephalopathy (1 paper, 2023). Encephalopathy is a term that means brain disease, damage, or malfunction. "When comparing GF between AC patients with and without encephalopathy, differences in the frequency of KIR3DL1+ were also discovered (97% vs. 71%, p = 0.050)." (PMID 37046435, 2023).
limited cutaneous systemic sclerosis (1 paper, 2024). Limited cutaneous systemic sclerosis (lcSSc) is a subtype of systemic sclerosis (SSc) characterized by the association of Raynaud's phenomenon with skin fibrosis limited to the hands, face, feet and forearms. "The protective HLA-B*44:03 allele against limited cutaneous systemic sclerosis is a member of the HLA-Bw4 KIR ligands and interacts with the specific receptor KIR3DL1." (PMID 38790215, 2024).
lung adenocarcinoma (1 paper, 2021). A carcinoma that arises from the lung and is characterized by the presence of malignant glandular epithelial cells. "Though many cancer types showed a consistent trend of increased expression of most checkpoints with an increase in EMT score, mesenchymal Lung Adenocarcinoma (LUAD) tissues were significantly enriched in all immune checkpoint markers (except KIR3DL1)." (PMID 35096592, 2021).
Multiple Organ Failure (1 paper, 2023). A progressive condition usually characterized by combined failure of several organs such as the lungs, liver, kidney, along with some clotting mechanisms, usually postinjury or postoperative. "In conclusion, our results show how the presence of the KIR2DL2/S2+, KIR2DL5+, and KIR3DL1+ genes in the patient could increase the frequency of death from multiple organ failure or graft failure." (PMID 37046435, 2023).
myeloid malignancy (1 paper, 2023). "Overall, these results sustain a deleterious effect of donor non-expressed KIR3DL1 alleles on relapse incidence after hHSCT only in the presence of myeloid malignancies." (PMID 37345091, 2023). "Interestingly, in patients treated for a myeloid malignancy, the cumulative incidence of relapse was significantly higher in those who received a graft with a non-expressed vs. expressed KIR3DL1 allotype (2 y relapse rate: 47 ± 14% vs. 24 ± 4%, p = 0.023)." (PMID 37345091, 2023).
myeloma (1 paper, 2015). "Concurrent analysis of inhibitory receptors (KIR2DL1, KIR2DL2/3, KIR3DL1 and NKG2A) and NK cell degranulation upon co-culture with myeloma cells revealed that KIR–ligand-mismatched NK cells degranulate more than matched subsets and that HLA-E abrogates degranulation of NKG2A+ subsets." (PMID 25920521, 2015).
ocular toxoplasmosis (1 paper, 2016). Ocular toxoplasmosis is an infection in the eye caused by the parasite, Toxoplasm a gondii. "The association observed for the KIR3DS1 with ocular toxoplasmosis can be explained by the absence of KIR3DL1, because 3DS1 and 3DL1 segregate as alleles of a single locus." (PMID 27827450, 2016). "Considering that numerous precautions were adopted to prevent bias in this study, we can safely say that the 3DS1 gene exerts a real influence on the development of ocular toxoplasmosis, even though KIR3DL1/S1 were not in Hardy-Weinberg equilibrium." (PMID 27827450, 2016). "In this study, KIR3DL1/S1 for the patient group that developed the ocular toxoplasmosis were not in Hardy-Weinberg equilibrium." (PMID 27827450, 2016).
ovarian endometriosis (1 paper, 2023). A non-neoplastic disorder characterized by the growth of endometrial tissue in the ovaries. "Specifically, the expression of KIR2DL4 was remarkably downregulated, while the expressions of PROK1, IGFBP1, RBP4, G2MB, KIR3DL1, and PRF1 were significantly upregulated in ovarian endometriosis." (PMID 37662927, 2023).
plague (1 paper, 2021). Plague is a severe bacterial infection caused by the gram-negative bacterium Yersinia pestis. "We observed a lower frequency of the HLA-B allotypes that can interact with KIR3DL1 in the modern individuals than we did in the plague victims, suggesting this combination could have been disadvantageous for individuals infected with Y. pestis." (PMID 34002224, 2021).
primary sclerosing cholangitis (1 paper, 2014). "HLA-Bw4 is the ligand for KIR3DL1, and is protective in MS and primary sclerosing cholangitis." (PMID 24988487, 2014).
sarcoidosis (1 paper, 2019). Sarcoidosis is a multisystemic disorder of unknown cause characterized by the formation of immune granulomas in involved organs. "In a recent WES study of three families sharing pediatric sarcoidosis, the KIR3DL1/KIR3DS1 in gene level was found to be shared in these families." (PMID 31921204, 2019).
ZIKV infection (1 paper, 2025). "In addition, CytoGLM identified increased KIR3DL1 and CD62L expression as predictive of acute ZIKV infection, and increased NTB-A, CD16, and Syk expression as predictive of healthy status." (PMID 41000887, 2025).
tumor (26 papers, 2010 to 2025). "Similar significance is observed in the KIR2DL2/HLA-C1 and KIR3DL1/HLA-Bw4 associations for mUC (OR p = 0.02, tumor shrinkage p = 0.005) as well." (PMID 36823323, 2023). "These cells were also clearly distinct from the tumor-associated CD69+IFNG+PRF1– and the dysfunctional/low cytotoxic NR4A1+ CD158a (KIR2DL1)+ CD158e (KIR3DL1)+ NK cell populations described in the other studies." (PMID 40530504, 2025). "We previously demonstrated that NK cells from eBL patients have increased density of inhibitory KIR3DL1, and have limited ability to kill target K562 tumor cells in vitro relative to healthy controls." (PMID 37647275, 2023). "Since NK cells are sensitive to cells with decreased expression of HLA-I, the strength of interaction of KIR3DL1 and HLA-B subtypes determines the degree of NK inhibition and hence their anti-tumor activities." (PMID 37647275, 2023). "NK cells with downregulation of KIR2DL2/L3, KIR2DL1 and KIR3DL1 presented less sensitivity to inhibitory signals from HLA-I presenting cancer cell lines, resulting in superior anti-tumor activity." (PMID 34072732, 2021). "Moreover, IOS-1002 adds another important mechanism since it binds to KIR3DL1 present on NK cells and leads to increased NK cell activation resulting in enhanced tumor cell killing." (PMID 39199672, 2024). "Considering this hypothesis, we expected KIR3DL1*High to provide a selective advantage through enhanced clearance of tumor cells, thus protecting individuals from eBL pathogenesis." (PMID 37647275, 2023). "In addition, patients with KIR2DL2 and HLA-C1 along with KIR3DL1 and HLA-Bw4 also showed improved duration of response and tumor shrinkage if they received maintenance, while patients without this genotype showed no such improvement when receiving maintenance." (PMID 30871628, 2019). "There was no significant improvement in duration of response or tumor shrinkage associated with maintenance treatment vs. non-maintenance for the patients that were not KIR3DL1+/Bw4+." (PMID 30871628, 2019). "Therefore, given the importance of NK cells in the control of viral infected and tumor cells, the functionality of different KIR3DL1 genotypes may provide insights into eBL pathogenesis." (PMID 37647275, 2023). "Notably, KIR3DL1+ NK cells exhibited rapid recovery (17.1% median at days 28-56, increasing to 41.7-86.0% by days 28-41), suggesting that KIR3DL1-HLA-B interactions may modulate anti-tumor immunity." (PMID 40726987, 2025). "By interacting with the LILRB1, LILRB2, KIR3DL1 and CD64 receptors, it enhances anti-tumor activity." (PMID 39199672, 2024). "Considering the complex regulation of NK cell responses, we will focus only on selected inhibitory receptors that are known to suppress NK cells functions in tumour, such as KIR2DL1–3, KIR3DL1–2, NKG2A/CD94, TIGIT, PD-1, LAG-3, and Tim-3." (PMID 35806034, 2022). "For patients that were KIR3DL1+/Bw4+, those that received the maintenance regimen showed significantly improved duration of response (p < 0.001) and % tumor shrinkage (p = 0.04) vs. those that did not receive maintenance." (PMID 30871628, 2019). "In NSCLC patients, tumor-infiltrating NK cells exhibit significantly elevated PD-1 expression, and these PD-1-positive NK cells concurrently coexpress multiple inhibitory receptors, including TIM-3, TIGIT, KIR2DL3, and KIR3DL1, resulting in compromised NK cell functionality." (PMID 40463500, 2025). "It has previously been shown that the high frequency of KIR3DL1 in BCC with more activating KIR receptors could help to kill tumor cells with low/absence of HLA class I expression." (PMID 31103021, 2019). "The KIR-HLA-ligand-matched KIR2DL1+ single-positive NK cell subset did not degranulate against those mouse-derived tumor cells, while the mismatched KIR2DL2/3+ and KIR3DL1+ single-positive populations degranulated." (PMID 34203549, 2021).
tumor (continued). "After univariate analysis, patients that underwent resective surgery of tumor, absence of KIR2DS5, and presence of KIR3DL1/HLA-Bw4-I80 showed a significant better OS (HR 1.5 to 2.8)." (PMID 24497922, 2014). "In addition, in this study, amongst patients that received rituximab maintenance, those that are KIR3DL1+/Bw4+ showed significantly improved TTRF, duration of response and tumor shrinkage than for those not KIR3DL1+/Bw4+." (PMID 30871628, 2019). "Similarly, amongst patients that received rituximab maintenance, those that are Group-1 (KIR2DL2+/C2+ and KIR3DL1+/Bw4+) showed improved TTRF, duration of response and tumor shrinkage than those that are Group-2 (not KIR2DL2+/C2+ and KIR3DL1+/Bw4+)." (PMID 30871628, 2019).
cancer (24 papers, 2012 to 2025). A tumor composed of atypical neoplastic, often pleomorphic cells that invade other tissues. "KIR3DL1 alleles have been reported to differentially influence outcomes within the context of other cancers." (PMID 37647275, 2023). "Sequence diversity of KIR3DL1/S1 and HLA class I allotypes diversifies human immune responses to specific infections, cancers, cancer treatment and transplantation." (PMID 35192601, 2022). "The expression of the inhibitory KIR family (KIR2DL1, KIR2DL3, KIR2DL4 and KIR3DL1) as well as the reduced expression of activating receptors such as DNAM-1, NKG2C, NKp46 and NKp30, are also associated with poor cancer prognosis." (PMID 34359767, 2021). "KIR3DL1/HLA-Bw4 axis influences also patients’ response to anticancer drugs based on antibodies with specificity directed against cancer cells." (PMID 34943866, 2021). "Among all the significant associations, CD36 expression was negatively correlated with ADORA2A and LAG3 in multiple cancer types, but positively associated with IDO1, IDO2, and KIR3DL1 in multiple cancers." (PMID 34234847, 2021). "As reported in several articles, the expression of inhibitory receptors, such NKG2A and KIR3DL1, on NK cells usually increases in different cancers." (PMID 27626490, 2016). "In addition, the genes included in the low-expression group were IDO2, ADORA2A, and KIR3DL1, as they showed a lower expression level in the majority of the cancer samples." (PMID 36157232, 2022). "However, it was also positively correlated with multiple inhibitory checkpoint molecules (IDO1, IDO2, and KIR3DL1) in multiple cancer types." (PMID 34234847, 2021). "Further research is required to determine the role of KIR3DL1 in different types of cancer." (PMID 24138752, 2013). "Likewise, specific combinations of KIR3DL1/S1 with HLA class I influence cancer susceptibilities non-uniformly across populations." (PMID 35192601, 2022). "Moreover, although the presence of KIR2DL5 significantly influences the presence of circulating NK cells differentially expressing KIR2DS1, KIR2DL2, and KIR3DL1, these cells appear to be more closely associated with the development of cancers in general, rather than with BC in particular." (PMID 40977889, 2025). "In this regard, two key areas of human health significantly impacted by the population differentiation of KIR3DL1/S1 combinatorial diversity with HLA are HIV research and treatment, and cancer therapy." (PMID 35192601, 2022).
infection (16 papers, 2011 to 2025). The state of being infected such as from the introduction of a foreign agent such as serum, vaccine, antigenic substance or organism. "Specifically, a positive association was observed between the risk of infection and the following genes: the inhibitory genes KIR2DL3 and KIR3DL1, along with the activating genes KIR2DS1 and KIR2DS4." (PMID 40244151, 2025). "In a population from Burkina Faso, KIR2DL2, KIR2DL3, and KIR2DS2 are associated with chronic stages of HBV infection, while KIR3DL1, KIR3DL2, KIR2DS1, and KIR2DP1 are associated with immunity against the infection." (PMID 40244151, 2025). "Binding between Bw4 on HLA-B expressed by a healthy cell and KIR3DL1, an inhibitory receptor, prevents the NK cell-mediated destruction that can occur when infection results in the downregulation of HLA-B50." (PMID 36823144, 2023). "The co-carriage of high expression KIR3DL1 genotypes with HLA-B*57 (*h/*y+B*57) is associated with both slow HIV disease progression and protection from infection." (PMID 25330014, 2014). "Our results indicate that compared to KIR3DS1 homozygotes, repeatedly HIV-exposed carriers of other KIR3DL1/S1 genotypes exhibit a faster time to infection." (PMID 25330014, 2014). "Dynamic changes in KIR3DL1-expressing NK or T cells during primary infection or reactivation of HSV-2 are also possible and could be studied using serial sampling." (PMID 35632760, 2022). "Also, as observed in adults, KIR3DL1-HLA-Bw4 has been associated with lower plasma viral load and higher CD4+ T-cell counts in all ages in paediatric infection." (PMID 34793581, 2021). "KIR3DL1/S1 + NK cells educated in the context of Bw4 alleles exhibit a stronger capacity to kill HIV-1-infected cells and, as a consequence, patients with KIR3DL1/S1 + NK cells exhibit lower viral load outcomes during the infection." (PMID 33042136, 2020). "Control of cancer, infection, autoimmunity, and reproduction have all been linked to KIR-HLA partnerships, and we have recently demonstrated that allele subtype variation for KIR3DL1 and HLA-Bw4 can have similar impacts." (PMID 31024561, 2019). "Carriers of a second genotype previously associated with protection from infection, i.e. *h/*y+B*57 showed a non-significant trend towards slower time to seroconversion compared with carriers of other KIR3DL1 homozygous and KIR3DL1/S1 heterozygous genotypes." (PMID 25330014, 2014). "Although presumptive, it is highly possible then that, in conjunction with their cognate ligands, KIR3DL1 may play a partial role in preventing infection or inhibiting the development of severe responses." (PMID 22216211, 2011). "Overall, these results demonstrate that, prior to infection, NK cells generated in the presence of more effective copies of KIR3DS1 and KIR3DL1 have enhanced HIV-1 antiviral activity." (PMID 22140359, 2011). "have linked the absence of KIR3DL1+HLA-Bw4+ and KIR3DL2+HLA-A3/11+ and the plethora of KIR2DS1+KIR2DS5+ to the severe infection." (PMID 37749597, 2023). "As flaviviruses are known to up‐regulate MHC class I 37, we propose that the increased expression of HLA‐B57 on target cells early in infection augments NS1 peptide presentation during the acute viraemic phase, thus enhancing KIR3DL1 interactions and maintaining NK cell inhibition." (PMID 26439909, 2016). "Alternatively, NS1 TET+ cells may represent a subset of NK cells that are restrained early in infection due to interactions between B57‐NS126–34 and KIR3DL1." (PMID 26439909, 2016).
infectious disease (4 papers, 2013 to 2023). A disorder directly resulting from the presence and activity of a microbial, viral, or parasitic agent in humans. "As a likely consequence of selective pressure providing resistance to infectious diseases, specific combinations of KIR3DL1/S1 and HLA associate, differentially across populations, with severity of specific viral infections or autoimmune diseases." (PMID 35192601, 2022). "In conclusion, the study of KIR3DL1-HLA-B aims to explain the mechanisms of immune modulation of NK cells immune response and may provide the basis for the design of more specific immunotherapeutic approaches in infectious diseases and immune disorders." (PMID 23984333, 2013). "It is unlikely that KIR3DL1*001 and HLA-B*51 rose to high frequency in Iran to protect specifically from an autoimmune disease, but this combination of HLA and KIR could also protect against specific infectious diseases." (PMID 32300348, 2020).